RN7SL383P (RNA, 7SL, cytoplasmic 383, pseudogene)
Gene: Miscellaneous RNA gene on chromosome 5 (44,716,193 to 44,716,486, forward strand). Ensembl gene ENSG00000263556.
Homologues: Orthologues: chimpanzee Metazoa_SRP (99% identical), macaque Metazoa_SRP (87% identical). Paralogues in human: RN7SL1 (85% identical), RN7SL2 (84% identical), RN7SL45P (84% identical), RN7SL3 (84% identical), RN7SL11P (83% identical), RN7SL664P (83% identical), RN7SL186P (82% identical), RN7SL296P (82% identical), RN7SL386P (82% identical), RN7SL47P (82% identical), RN7SL126P (82% identical), RN7SL304P (82% identical), and 703 more.